HIF1A (hypoxia inducible factor 1 subunit alpha)
Diseases named in the same sentence as HIF1A in open-access papers (continued):
Sharing a sentence is not in itself a finding about the gene and the disease.
cancer (continued). "Combining cyclin-dependent kinase (CDK) inhibitors with heat shock protein 90 (HSP-90) inhibitors presents a promising approach to destabilizing hypoxia-inducible factor 1-alpha (HIF1α) and inhibiting cancer cell growth." (PMID 39697237, 2024). "4-HNE increased the growth of cancer cells and upregulated the level of HIF-1α through the inhibition of Sirtuin-3 (SIRT3)." (PMID 38674143, 2024). "Intermittent hypoxia (IH) in OSA promotes cancer progression by upregulating HIF-1α and transforming growth factor β1 (TGF-β1), which alter cytokine levels, increase TNF-α and IL-10, and decrease IL-17, suppressing antitumor immunity." (PMID 39070143, 2024). "Acriflavine’s potential in helping control cancer arises from its inhibition of HIF-1α’s DNA-binding capabilities." (PMID 39493156, 2024). "This insight into miRNA involvement complements the therapeutic strategies that incorporate CDK4/6 inhibition, as reduced HIF1α levels further sensitizes tumors to other anti-cancer agents." (PMID 39697237, 2024). "There is a functional link between HIF-1α and H19 that determines H19 elevation in hypoxic cancer cells." (PMID 38987833, 2024). "Understanding these mechanisms is key to developing effective HIF-1α inhibitors for cancer and other diseases." (PMID 39683818, 2024). "Activation of HIF-1α has been demonstrated to accelerate cancer advancement by facilitating angiogenesis." (PMID 38792080, 2024). "The PI3K/AKT/mTOR signalling pathway contributes to the development of cancers by regulating HIF-1a activation; blocking the PI3K/AKT pathway inhibits HIF-1a expression and promotes its degradation." (PMID 38893278, 2024). "Various studies have shown that HIF-1α upregulates the expression of the mitophagy receptor protein BNIP3L/NIX to promote mitochondrial clearance under hypoxic conditions in several cancer cell lines." (PMID 38257395, 2024). "As a result, HIF-1α enables cancer cells to adapt and survive in hypoxic conditions by promoting the expression of genes involved in glycolysis, angiogenesis, cell proliferation, and survival." (PMID 38474118, 2024). "This adapter protein is primarily investigated in cancer, where it is recognized for enhancing aerobic ATP production through the stabilization of hypoxia-inducible factor (HIF)-1α." (PMID 38396894, 2024). "Increased HIF-1α expression can be observed in many cancers, such as stomach, bladder, colon, pancreas, kidney, ovary, and brain cancer." (PMID 39275392, 2024). "HIF-1α also plays a significant role in various diseases that generate hypoxic microenvironments, including cancer, stroke, and heart disease." (PMID 39766299, 2024). "In the TME, macrophage HIF-1α expression plays a role in polarization to protumor TAMs, which promote cancer cell migration and metastasis." (PMID 38689086, 2024). "HIF-1α, also known as hypoxia-inducible factor-1α, serves as the primary nuclear transcription factor responsible for the hypoxic reaction in cancer cells." (PMID 38842687, 2024). "In common with TRIB3, a potential link between TRIB2 and HIF-1α has been reported, as depletion of TRIB2 significantly decreased the effect of TNF-α on HIF-1α stability and accumulation in multiple cancer cell lines." (PMID 38896446, 2024). "This work focused on the co-delivery of Axitinib and Celastrol (an anti-cancer drug that induces the inhibition of HIF-1α) to target angiogenesis and mitochondrial-based apoptosis in cancer." (PMID 39624468, 2024). "Not all cell lineages exhibit uniform susceptibility to oxygen tension, ranging from those with minimal sensitivity to those showing constitutive expression of HIF1a, often due to genetic alterations, as observed in highly modified cancer cells." (PMID 38976146, 2024). "Understanding the regulation of HIF-1α is essential for developing therapeutic strategies targeting hypoxia-related diseases, including cancer." (PMID 39493156, 2024).
cancer (continued). "These examples underscore the intricate roles of ncRNAs in shaping the dynamics of HIF-1α signaling in cancers." (PMID 38279330, 2024). "By upregulating enzymes and transporters involved in glycolysis, lactate production, and fructose metabolism, HIF1α enhances the metabolic flexibility of cancer cells." (PMID 39107723, 2024). "These DNMTs gene expressions were decreased in HIF‐1A silenced cells and upregulated in HIF‐1A overexpressed A549 cancer cells, indicating the role of HIF‐1A in regulating DNMTs expression in a hypoxic state." (PMID 35658112, 2024). "Angiogenesis is activated by HIF-1α, which correlates with heightened cancer aggressiveness and worsened clinical outcomes." (PMID 39001366, 2024). "This CMA assists cancer survival and progression in the hypoxic microenvironment of tumors by hypoxia-inducible factor-1 alpha (HIF-1α) degradation." (PMID 38339390, 2024). "Expression of the PDK1 gene is upregulated by hypoxia-inducible factor-1α (HIF-1α), an important mechanism by which cancer cells switch from oxidative to anaerobic glucose metabolism." (PMID 39080182, 2024). "The sensor of hypoxia HIF-1α also regulates the characteristics of cancer stem cells, including their ability to undergo EMT, differentiation, and self-renewal." (PMID 38904007, 2024). "Metabolic adaptations: HIF-1α engulfs metabolic adaptation in cancer cells where the ability of producing energy through glycolysis in hypoxic conditions is enhanced." (PMID 39493156, 2024). "Research has demonstrated that HIF-1α triggers increased expression of PD-L1 in cancer and myeloid cells." (PMID 39421736, 2024). "Increased motility: HIF-1α enhances cancer cell migration and invasion by changing cytoarchitecture remodeling and changes in migration-related proteins." (PMID 39493156, 2024). "Inhibiting CDK1 disrupts this phosphorylation, leading to decreased HIF1α stability and impairing cancer cell survival mechanisms." (PMID 39697237, 2024). "Cancer cells are in high demand for fatty acids, so HIF-1α upregulates fatty acid (FA)-binding proteins FABP3 and FABP7, increasing FA transport in cells." (PMID 38674143, 2024). "miRNA modulation: Certain miRNAs can directly target HIF-1α or its downstream effectors, impacting cancer cell proliferation and survival." (PMID 39493156, 2024). "Crucially, we introduce a novel mechanism wherein FGF7 serves as a critical regulatory factor facilitating crosstalk between CAFs and cancer cells, thereby promoting the progression of OC via activation of the HIF1α/EMT signaling axis." (PMID 38491511, 2024). "The stimulation of the HIF-1α/SLC7A11 pathway decreased HYSA’s anti-cancer activities in MG63 cells." (PMID 38686047, 2024). "CITED2 is a crucial mediator of the HIF1A hypoxic response, which, in cancer, is indicated to serve as a co-activator of SMAD2/3 affecting TGF-β signaling." (PMID 38339304, 2024). "Regulatory mechanisms on AMPK expression have been seen in cancer cells along with key signaling molecules such as mammalian Target Of Rapamycin (mTOR) (Raptor) or Hypoxia-Inducible Factor 1-alpha (HIF-1α) which control AMPK protein expression." (PMID 38555305, 2024). "PFKP is also subject to regulation by HIF-1α at the translational level, promoting cancer cell invasion." (PMID 38982480, 2024). "Oncogenes like c-Myc and HIF-1α are master inducers of cancer glycolysis via the direct or indirect transactivation of cancer glycolytic genes." (PMID 39273552, 2024). "Contrary to findings that HIF-1α is downregulated in IDH mutant cancers, many others have shown that HIF-1α is upregulated in IDH mutant cells, cells treated with exogenous 2-HG, IDH mutant tumors, and brains of mouse embryos expressing IDH1-R132H." (PMID 39596840, 2024). "Targeting NRF2 with shRNA resulted in the downregulation of HIF-1α and glycolytic genes, ultimately leading to the suppression of cancer proliferation." (PMID 38424190, 2024).
cancer (continued). "Indirect inhibitors aim to downregulate HIF-1α transcription or translation, reduce HIF-1α stability, or prevent its degradation, offering potential pathways to mitigate drug resistance in cancer treatment." (PMID 38799423, 2024). "There is great promise for bypassing resistance mechanisms and boosting antitumor immunity when HIF-1α targeting is combined with immunotherapeutic approaches such as immune checkpoint inhibitors and cancer vaccinations." (PMID 39493156, 2024). "Evidence has shown that the expression of A2BAR is induced by HIF-1α in endothelial cells, dendritic cells, and cancer cells after hypoxic damage." (PMID 38790642, 2024). "The correlation between lactate-MCT/HIF1α and metabolic reprogramming of macrophage polarization in gastric cancer has been observed in interactions between cancer cells and immune cells." (PMID 39107723, 2024). "The expressions of angiotensin-converting enzyme 2 (ACE2) and hypoxia-inducible factor 1 α (HIF1α) in cancer tissue are known as predictive markers of cancer recurrence." (PMID 39273283, 2024). "The elevated expression level of HIF-1α has been observed in various primary and secondary malignant tumors, making it a valuable biomarker and potential target for clinical diagnosis, targeted treatment, and prognosis evaluation in numerous diseases." (PMID 38327979, 2024). "HIF1A, a critical transcription factor for cancer cell survival, orchestrates the expression of genes related to metabolism and survival, enabling adaptation to adverse microenvironments." (PMID 39436710, 2024). "Together, our data propose the usefulness of HIF-1α as a prognostic and/or predictive biomarker, as well as in personalized cancer therapy." (PMID 38921041, 2024). "HIF-1α is involved in regulating biventricular metabolic symbiosis between synthetic metabolic cancer cells and catabolic stromal fibroblasts." (PMID 38799423, 2024). "Glycolytic cancer cells can induce TAMs to express VEGF in a HIF-1α-dependent manner and promote M2 polarization via lactate secretion, further enhancing aerobic glycolysis in PDAC cells." (PMID 39430253, 2024). "Intriguingly, many cancers exhibit constitutive activation of HIF-1α even in normoxic conditions, and Akt is known to participate in this process via mTORC1 upregulation 117-122." (PMID 38904014, 2024). "Chrysin, a natural compound commonly used in cancer treatment, has shown effectiveness in PCa therapy by downregulating HIF‐1α, thereby inhibiting tumor cell progression under hypoxic conditions." (PMID 39691874, 2024). "In this process, cancer cells must adhere to ECs and pass through the EC-EC interactions with the assistance of HIF-1α." (PMID 39434182, 2024). "Previous studies showed that HIF-1α was hyperactive in TNBC to promote cancer growth and metastasis, but the mechanisms or factors contributing to the high basal HIF-1α in TNBC remain elusive." (PMID 38658533, 2024). "The stiffness of the extracellular matrix (ECM), pH gradients, and chemical balance changes that contribute to multiple cancer hallmarks are closely regulated by intratumoral O2 tension through its controlled by HIF-1α." (PMID 38766303, 2024). "In this study, we observed that ST3G5high cancer cells secreted exosomes containing HIF1α and glycolytic enzymes." (PMID 37716915, 2024). "Monocyte migration is significantly hampered in miR‐210‐3p mimic‐transfected HIF‐1A silenced cancer cells." (PMID 35658112, 2024). "In cancer cells, HIF-1α expression is related to the NLRP3 inflammasome, the Warburg effect, and EMT/metastasis." (PMID 38904007, 2024). "Moderate increases in reactive oxygen species (ROS) levels in hypoxic cancer cells stabilize HIF-1α and mediate various tumorigenic-related signaling pathways, including AKT, NF-κB, AMPK, and Notch69." (PMID 39738201, 2024). "In these conditions, hypoxia-inducible factor 1 alpha (HIF-1α) is activated and acts as a transcription factor that regulates cancer cell adaptation to O2 and nutrient deprivation." (PMID 38766303, 2024).
cancer (continued). "Hypoxia-inducible factor 1-alpha (HIF-1α) immunohistochemistry of cancer-free fallopian tube specimens allowed a comparison of proximal versus distal portions." (PMID 38539519, 2024). "Leveraging the relationship between HIF1α and the TME through the SMURF2-HIF1α axis offers a multifaceted strategy for cancer treatment, particularly beneficial in tumors resistant to traditional therapies targeting the von Hippel-Lindau-HIF1α pathway." (PMID 39697237, 2024). "Hypoxia is a common condition in most solid tumors, and extensive research has highlighted the crucial role of HIF-1α in the regulation of various EMT transcription factors that contribute to cancer cell progression." (PMID 38339408, 2024). "PTEN loss results in deregulation of the nuclear factor kappa-light-chain-enhancer of activated B cells (NF-κB) and induces hypoxia-inducible factor 1-alpha (HIF-1α) expression in various cancers." (PMID 39063014, 2024). "Specifically, SMURF2’s role as an E3 ubiquitin ligase in regulating HIF1α stability and activity is central to its function in cancer." (PMID 39697237, 2024). "As UCHL1 can deubiquitinate and stabilise HIF1α in cancer cell lines, we sought to determine if there are changes in HIF1α levels during HSC transdifferentiation." (PMID 38808772, 2024). "This therapeutic approach has been studied in other types of cancers, too, and demonstrated increased effectiveness by affecting HIF-1α." (PMID 39055895, 2024). "OPN promotes cell survival and increases HIF-1α expression through the PI3K/Akt pathway in cancer cells." (PMID 39408927, 2024). "The resultant increase in the transcriptional activity of HIF-1α fuels aerobic glycolysis in cancer cells." (PMID 38339256, 2024). "It has been shown that PVT1 upregulates simultaneously with hypoxia inducible factor 1 subunit alpha (HIF-1α) in hypoxic-cancer cells." (PMID 38559560, 2024). "Under hypoxic conditions, overexpression of hypoxia-inducible factor-1α (HIF-1α) occurs alongside a notable decrease in miRNA-141 expression, facilitating cancer invasion." (PMID 38927885, 2024). "It is also worth noting that HIF-1α expression is elevated in cancer cells under normoxic conditions and exposure to extracellular stimuli like growth factors." (PMID 38474118, 2024). "In summary, these data revealed that activation of HIF-1α pathway promoted cancer stemness and LR in HCC." (PMID 39300073, 2024). "The targeting ability of conditional Ab was further analyzed by costaining excised cancer tissues with Abs against hypoxia inducible factor 1 alpha (HIF‐1α), microvascular marker CD31 and hypoxia marker pimonidazole." (PMID 38469549, 2024). "Among them, HIF-1α has significant implications in the case of cancer, especially in hypoxic areas within tumors, which aid in the reorganization of the metabolism in cancer cells." (PMID 39099978, 2024). "EGLN3, identified through string analysis, has emerged as a potential therapeutic target for modulating HIF-1α function and impeding cancer progression." (PMID 38542288, 2024). "HIF-1α, a transcription factor that functions as a master regulator of oxygen homeostasis, has been found to be upregulated in various cancers, including OC." (PMID 38491511, 2024). "Targeting HIF-1α represents a promising approach to overcome hypoxia-induced drug resistance in cancer." (PMID 39459028, 2024). "Normally HIF-1α levels go up only under hypoxic conditions whereas, in cancer cells, HIF-1α levels go up under normoxic conditions." (PMID 38339256, 2024). "Particularly several of the pathways expected to be activated by bacterial contact with human cells (step 2) have the potential to increase activity and/or stability of HIF-1α and contribute to cancer progression." (PMID 38535967, 2024). "In this work, we propose a possible mechanism through which E6 and E7 participate in metabolic reprogramming in cancer by preventing the degradation of HIF-1α, the key subunit in forming the active transcription factor HIF-1." (PMID 38921041, 2024).
cancer (continued). "The results of Venn plot showed that three overlapping genes were identified, and we chose HIF‐1α for further study as previous studies have shown an essential role of HIF‐1α in cancer progression." (PMID 38639382, 2024). "The notion of an increase in HIF-1α resulting from metabolically driven oncogenesis such as IDH is supported by cancers driven by a similar mechanism." (PMID 39596840, 2024). "Lactate produced during the Warburg effect stimulates HIF‐1α expression, thereby exacerbating the malignant phenotype of cancer." (PMID 39417674, 2024). "Once activated, HIF-1α initiates a cascade of molecular events that promote angiogenesis, metabolic adaptation, and metastatic potential in cancer cells." (PMID 38491511, 2024). "Wnt/planar cell polarity (PCP), notch-jagged signaling, and hypoxia-inducible factor 1 alpha (HIF-1α) signaling are some defined key signaling pathways that can mediate collective-cell migration during cancer metastasis." (PMID 38715921, 2024). "CD73, which is regulated by HIF-1α, emerges as a promising target for suppressing cancer progression." (PMID 39459028, 2024). "The results revealed that the HIF-1α signaling, arginine, and proline pathways enriched in the target genes were related to the tumorigenesis of several cancers, including CRC." (PMID 38563016, 2024). "Under hypoxia conditions, PHD activity is impaired, and the formation of the complex (VCB-CR) is prevented, recognition of HIF-1α is impaired, HIF-1α is stabilized, and a hyperglycolytic phenotype is generated in cancer cells." (PMID 38921041, 2024). "Since nuclear PKM2 has been reported as an HIF-1α cofactor in cancer cells, we examined this interaction in tubular cells." (PMID 39226171, 2024). "Prolonged stabilization of HIF-1α, even under normoxic conditions, can lead to mitochondrial adaptations that support cancer cell stemness and tumorigenicity." (PMID 39408832, 2024). "HIF-1α levels are elevated in cancer cells even under normoxic conditions because of the inhibition of PHD2 by lactate (pseudohypoxia)." (PMID 38339256, 2024). "Several studies have demonstrated that HIF-1α expression increases in many cancers and is important in cancer progression." (PMID 38892084, 2024). "We identified that increased cancer stemness driven by the hypoxia-inducible factor-1α (HIF-1α) pathway activation is responsible for acquired LR in HCC." (PMID 39300073, 2024). "HIF1α also promotes cancer cell survival and therapy resistance by inhibiting apoptosis and encouraging autophagy through the upregulation of genes that prevent apoptosis and support autophagy under treatment stress." (PMID 39697237, 2024). "In hypoxic conditions, HIF-1α activates glycolytic genes like HK-2, enhancing lactate production, a process that is often upregulated in cancer." (PMID 39683818, 2024). "Because of its significant metabolism-regulating abilities, HIF-1α has the potential to be a therapeutic target for a number of illnesses and ailments, such as cancer, ischemia, chronic inflammation, and any other pathologies caused by metabolic disturbances." (PMID 39099978, 2024). "The dependency of cancer cells on HIF factors when growing in hypoxia points to HIF-1α as a candidate for pharmacological intervention." (PMID 38341408, 2024). "BMAT can play a critical role in PCa cell metabolism by inducing glycolytic enzymes via activation of HIF-1α and promoting a Warburg phenotype, the process by which cancer cells consume glucose for energy production." (PMID 38625510, 2024). "We evaluate antisense efficacyusing HIF1a, a hypoxic indicator upregulated in many cancers, anddemonstrate dose-dependent activity through RT-qPCR." (PMID 38346399, 2024).